DOCK1 (dedicator of cytokinesis 1)
Diseases named in the same sentence as DOCK1 in open-access papers (continued):
Sharing a sentence is not in itself a finding about the gene and the disease.
tumor (continued). "Moreover, the level of Dock1, Snail, and Vimentin in the tumor xenograft were downregulated, but E-cadherin level was upregulated in the mice that was inoculated with SiDock1/MDA-MB-231 or miR-486-5p/MDA-MB-231 cells than Scr/ MDA-MB-231 or NC/MDA-MB-231 cells." (PMID 31528235, 2019). "Here, we found that DOCK1 was significantly upregulated in HCC and that targeting DOCK1 with selective inhibitor resulted in strong synergistic anti-tumor effects when administered with metformin." (PMID 35217990, 2022). "It warrants mention that although DOCK1 expression is widely upregulated in HCC patients, tumor heterogeneity still results in differential accumulation of DOCK1 among HCC samples, with some patients exhibiting very low, even undetectable, levels of DOCK1." (PMID 35217990, 2022). "Collectively, these data suggest that DOCK1 is upregulated in HCC, and its degree of upregulation can determine the anti-tumor effectiveness of metformin." (PMID 35217990, 2022). "These tumours were also characterised by increased tyrosine phosphorylation of Ptrf/cavin, which is localised with Cav1 to caveolae, and of the RTK Axl and the docking protein Dock1." (PMID 25200860, 2014). "Although DOCK1 selective inhibitors have not yet undergone clinical trials, our study showed that DOCK1-specific inhibitors have strong apparent potential for use as efficient anti-tumor drugs through synergistic enhancement of the anti-tumor effects of metformin." (PMID 35217990, 2022).
cancer (25 papers, 2013 to 2025). A tumor composed of atypical neoplastic, often pleomorphic cells that invade other tissues. "DOCK1, an important regulator of cell progression, is associated with metastatic processes in human cancer and accelerates cancer progression." (PMID 39967686, 2025). "Such examples include DOCK-controlled motility resulting in metastasis in cancer (DOCK1), deficient axon organization potentially resulting in a neurological disorder (DOCK4), or deficient immune cell migration resulting in immunodeficiency (DOCK8)." (PMID 33684443, 2021). "DOCK1 expression and mutations have been reported from a number of cancers." (PMID 32322580, 2020). "Hence, DOCK1 inhibition could be an approach for the treatment of cancers associated with the Rac1 P29S oncogenic mutation." (PMID 32322580, 2020). "Multiple signaling pathways were confirmed to take part in the mechanism of DOCK1 on mediating biological behavior of cancer." (PMID 38438882, 2024). "DOCK1, a member of the DOCK family, has been implicated in cancer cell metastasis and intestinal epithelial cell migration." (PMID 37967942, 2024). "Selective knockdown of DOCK1 abolished cell motility and cell invasion and suppressed cancer growth and metastasis in a mouse model." (PMID 35241089, 2022). "Taken together, these results demonstrated that metformin functions in the phosphorylation of DOCK1, resulting in the activation of RAC1, and consequently, deficiency of DOCK1 sensitizes cancer cells to metformin." (PMID 35217990, 2022). "Combined treatment of metformin with DOCK1-selective inhibitor led to the sensitization of cancer cells to metformin both in vitro and in vivo." (PMID 35217990, 2022). "Since stemness is an established property pertaining to drug resistance and poor prognosis in cancer patients, these data provided an explanation for the unfavorable prognostic impact of DOCK1 over-expression in AML." (PMID 29069784, 2017). "DOCK1 has emerged as a key driver of cancer metastasis in multiple cancer types." (PMID 37967942, 2024). "Accumulating studies demonstrated that DOCK1 might contribute to the progression of cancer biological behavior." (PMID 38438882, 2024). "Increasing studies found that DOCK1 participated in the metastasis of cancer cells." (PMID 38438882, 2024). "DOCK1, a guanine nucleotide exchange factor, is dysregulated in various cancers." (PMID 38438882, 2024). "The most common GEFs implicated in cancer are T-cell lymphoma invasion and metastasis 1 (Tiam1), Trio, Vav1/2/3, Ect2, Phosphatidylinositol 3,4,5-trisphosphate (PIP3)-dependent Rac exchanger 1 (P-Rex1), and Dock1." (PMID 32322580, 2020). "In order to elucidate the mechanism of DOCK1 in cancer metastasis, we first analyzed the transcriptomic changes using a clinical database of human TNBC and found that the increase in DOCK1 expression was highly correlated with the poor survival rate of TNBC patients." (PMID 31717460, 2019). "Dedicator of cytokinesis 1 (DOCK1) is a critical regulator of cancer metastasis." (PMID 31717460, 2019). "In addition, 1-[2-(3′-(trifluoromethyl)-(1,1′-biphenyl)-4-yl)-2-oxoethyl]-5-pyrrolidinylsulfonyl-2 (1H)-pyridone (TBOPP), a selective inhibitor of Dedicator of cytokinesis 1(DOCK1), inhibits macropinocytosis and invasion in cancer cells and also suppresses cancer growth and metastasis in vivo." (PMID 36750864, 2023). "Notably, among the 18 GO terms, four terms were related to small GTPase activity, which suggested that the pathway for small GTPase activity may be involved in DOCK1 suppression induced sensitization of cancer cells to metformin." (PMID 35217990, 2022). "Recently, the DOCK1 selective inhibitor TBOPP was identified and reported to suppress cancer cell growth and metastasis in vivo." (PMID 35217990, 2022).
cancer (continued). "However, combining metformin with the DOCK1 inhibitor (TBOPP) significantly reduces HCC cell viability, suggesting a synergistic approach to enhancing metformin’s anti-cancer effects." (PMID 38997696, 2024). "To further clarify whether shDOCK1 sensitized cancer cells to metformin via its canonical GEF function, we ectopically expressed DOCK1 carrying a DHR2 domain deletion (DOCK1△DHR2) in PLC cells with endogenous DOCK1 knockdown." (PMID 35217990, 2022). "In CLBC cells, DOCK1 mediates cell growth and motility through down-regulating the expression of claudin-1 via the RRP1B–DNMT–claudin-1 pathway, and claudin-1 serves as an important effector in DOCK1-mediated cancer progression and metastasis." (PMID 31717460, 2019). "While the ubiquitous expression of DOCK1, as well as its apparent importance to neural cell development, could pose problems when targeting tissue-specific disorders, inhibition of this GEF could have beneficial effects in cancer treatment." (PMID 33684443, 2021).
DOCK1 also shares sentences with these, for which no sentence is quoted: Alzheimer disease (2 papers); Chlamydia infection (2); gastric cancer (2); oral squamous cell carcinoma (2); allergic asthma (1); allergic reactions (1); Anxiety (1); cervical cancer (1); depression (1); diabetes (1); head and neck squamous cell carcinoma (1); hemorrhage (1); infection (1); infectious disease (1); lung adenocarcinoma (1); malignant glioma (1); mesenchymal tumours (1); nasopharyngeal carcinoma (1); rheumatoid arthritis (1); Salmonella Infections (1); thyroid cancer (1).